MIR143 (microRNA 143)
Synonyms: hsa-mir-143; MIRN143; mir-143
Gene: MicroRNA gene on chromosome 5 (149,428,918 to 149,429,023, forward strand). Ensembl gene ENSG00000284182.
Gene Ontology:
Biological process: miRNA-mediated post-transcriptional gene silencing
Cellular component: RISC complex
Homologues: Orthologues: chimpanzee ptr-mir-143 (99% identical), macaque mml-mir-143 (99% identical), pig ssc-mir-143 (70% identical), tropical clawed frog xtr-mir-143 (70% identical), zebrafish dre-mir-143 (69% identical), guinea pig MIR143 (59% identical), mouse Mir143 (59% identical), dog MIR143 (57% identical), rabbit MIR143 (57% identical).
Diseases named in the same sentence as MIR143 in open-access papers:
MIR143 is named in the same sentence as 13 diseases in open-access papers, as found by Europe PMC text mining. Sharing a sentence is not in itself a finding about the gene and the disease. The quoted sentences say what the papers report.
glomus tumor (2 papers, 2014 to 2025). A rare benign or malignant mesenchymal neoplasm arising from cells that resemble the modified smooth muscle cells of the glomus body. "Other reports, show an association of MIR143 gene with NOTCH1-3; suggesting that the mechanism of MIR143–NOTCH1-3 tumorigenesis is through oncogenic activation of NOTCH driven by the very strong MIR143 promoter in malignant glomus tumors." (PMID 25717438, 2014).
bone marrow cancer (1 paper, 2023). "DO and KEGG analysis indicated that MIR143-3p was involved in bone marrow cancer, including myeloid leukemia." (PMID 37237254, 2023).
Hirschsprung disease (1 paper, 2020). Hirschsprung disease (HSCR) is a congenital intestinal motility disorder that is characterized by signs of intestinal obstruction due to the presence of an aganglionic segment of variable extent in the terminal part of the colon. "The MIR143 host gene (MIR143HG) is a precursor of miR-143 and miR-145, and is overexpressed in colon tissues of patients with Hirschsprung disease (HSCR)." (PMID 32806768, 2020).
male infertility (1 paper, 2018). The inability of the male to effect fertilization of an ovum after a specified period of unprotected intercourse. "MIR143 and MIR145 expression was monitored in FF from an experimental cohort of women pursuing to assisted reproductive technology (ART) with signs of DOR, whereas women pursuing to ART as a consequence of male infertility represented the control group." (PMID 30534420, 2018).
melanoma (1 paper, 2019). A malignant, usually aggressive tumor composed of atypical, neoplastic melanocytes. "As we do not have access to an appropriate wild type melanoma cell line control, further studies on MIR143 SNPs in melanoma may be beneficial." (PMID 30818878, 2019).
prostate carcinoma (1 paper, 2020). A carcinoma that arises from epithelial cells of the prostate gland. "Later work showed that Mir143 has a tumor suppressor role in prostate cancer by controlling cell proliferation and survival through modulation of ERK5, and that Mir143 expression inversely correlates with nuclear ERK5 immunoreactivity in clinical prostate cancer." (PMID 32023850, 2020).
type 2 diabetes (1 paper, 2024). "A possible trend toward significance was found in the expression of the MIR126 gene (p = 0.051), the MIR133A1 gene (p = 0.076), the MIR143 gene (p = 0.08), and the MIR320A gene (p = 0.095) in patients with type 2 diabetes." (PMID 38256676, 2024). "The value of MIR143 gene expression showed a statistical trend toward significance in patients with type 2 diabetes (median: 0.547; mean: 0.494; standard deviation: 1.047) compared to patients without type 2 diabetes (median: 0.205; mean: 0.071; standard deviation: 1.148)." (PMID 38256676, 2024).
tumor (5 papers, 2020 to 2023). "Mechanistically, MIR155 suppresses MIR143, a well-documented tumor suppressor, via targeting the activation of STAT3 gene targeting c/EBPB (a transcriptional activator for MIR143)." (PMID 33920789, 2021). "MIR143-3p has been reported to function as a tumor suppressor." (PMID 37237254, 2023). "MIR143/145 and MIR1 may help to fine-tune cytoskeletal homeostasis and allow migration of hLMS tumor cells." (PMID 36672483, 2023).
cancer (3 papers, 2021 to 2025). A tumor composed of atypical neoplastic, often pleomorphic cells that invade other tissues. "These ATF3-induced tumors were also found to have reduced expression of Mir145 and Mir143, leading to upregulation of the transcription factors Klf4 and Sox2 and the cancer stem cell-related gene Kras, respectively." (PMID 33652981, 2021). "The most potent of these variants may be mutations in well-known cancer-related miRNA genes, such as MIR16-2, MIR143, or MIR155, or mutations recurring in specific miRNA genes." (PMID 40867048, 2025).
MIR143 also shares sentences with these, for which no sentence is quoted: breast cancer (2 papers); colon cancer (1); myeloid leukemia (1); rhabdomyosarcoma (1).